SYNPO2 (synaptopodin 2)
Diseases named in the same sentence as SYNPO2 in open-access papers (continued):
Sharing a sentence is not in itself a finding about the gene and the disease.
meningioma (1 paper, 2017). A generally slow growing tumor attached to the dura mater. "In the canine genome, these lie in a contingent region of canine chromosome 1 and in our study, a number of meningiomas had increases in both SYNPO2 mRNA complementary to ZPF36 and FOSB." (PMID 29073243, 2017).
mental disorder (1 paper, 2021). A disease that has its basis in the disruption of mental process. "SYNPO2 is mainly expressed in human brain tissue and has been demonstrated to associate with several mental disorders." (PMID 33807197, 2021).
metastatic melanoma (1 paper, 2023). A melanoma that has spread from its primary site to another anatomic site. "In metastatic melanomas, a significant increase in SYNPO2 promoter methylation level was observed compared to non-metastatic melanoma, and SYNPO2 promoter hypermethylation was highly correlated with poor prognosis." (PMID 37544991, 2023).
nemaline myopathy (1 paper, 2023). Nemaline myopathy (NM) encompasses a large spectrum of myopathies characterized by hypotonia, weakness and depressed or absent deep tendon reflexes, with pathologic evidence of nemaline bodies (rods) on muscle biopsy. "Indeed, in two different patients with nemaline myopathy, SYNPO2 colocalized with α-actinin in the rods." (PMID 38201288, 2023).
nephrotic syndrome (1 paper, 2023). A collection of symptoms that include severe edema, proteinuria, and hypoalbuminemia; it is indicative of renal dysfunction. "An association between SYNPO2 SNPs and immunity has been found, with SYNPO2 rs1038770 associated with total IgE levels and mutations detected in patients with nephrotic syndrome." (PMID 37544991, 2023).
neurogenic muscular atrophy (1 paper, 2023). "In addition, our previous work indicated that SYNPO2 is overrepresented in the central and intermediate zone of target fibers in the skeletal muscles of patients with neurogenic muscular atrophy." (PMID 38201288, 2023).
prostate tumors (1 paper, 2023). "Collectively, it is very likely that simply the lack of smooth muscle cells in high-grade prostate tumors may cause the apparent absence of SYNPO2 protein in prostate (and other) tumor biopsies." (PMID 38201288, 2023).
Schistosoma haematobium infection (1 paper, 2025). "In the context of Schistosoma haematobium infection, the down-regulation of SYNPO2 observed in our study may reflect a protective role against parasite evasion of the immune response." (PMID 40853910, 2025). "Machine learning emphasized SYNPO2, CD276, α2M, LCAT, and hnRNPM as the most discriminating biomarkers for Schistosoma haematobium infection." (PMID 40853910, 2025).
schizophrenia (1 paper, 2021). A major psychotic disorder characterized by abnormalities in the perception or expression of reality. "The GWASdb SNP-Phenotype association dataset showed that SYNPO2 was associated with the schizophrenia phenotype in GWAS datasets." (PMID 33807197, 2021).
tumor (24 papers, 2009 to 2025). "High methylation of the SYNPO2 promoter region and low expression of its protein can be used alone or in combination with other factors for tumor diagnosis and risk assessment." (PMID 37544991, 2023). "SYNPO2 (known as myopodin), encodes an actin-binding protein, and has been characterized as a tumour suppressor which positively regulates ROCK." (PMID 36833199, 2023). "SYNPO2, also known as synapsin 2 or myopod, encodes an actin‐binding protein and has been characterized as a tumor suppressor for aggressive cancers." (PMID 35028969, 2022). "Synpo2 is the second identified member of the podin family of actin binding proteins, and is associated with invasive tumor development." (PMID 25883213, 2015). "Loss of Synpo2 expression correlates with increased invasive tumor development, an observation seemingly at odds with the serum-stimulated, pro-migratory phenotype that results when Synpo2 expression is restored in PC3 cells." (PMID 25883213, 2015). "Immunohistochemistry suggests that SYNPO2‐positive expression in tumour cells, fibroblasts, inflammatory cell may be associated with promoting peritoneal metastasis in GC." (PMID 37605453, 2023). "In addition, the potential and value of SYNPO2 single nucleotide polymorphisms (SNPs) and promoter region methylation as tumor diagnostic markers are explored." (PMID 37544991, 2023). "In humans, SYNPO2 functions as a potential tumor suppressor, regulating autophagy and cancer progression, with high expression levels linked to a favorable prognosis in most cancers." (PMID 40906375, 2025). "In most cancers, high SYNPO2 expression is positively correlated with a good prognosis, suggesting its role as a novel tumor suppressor." (PMID 37544991, 2023). "Recent studies have shown that the expression of SYNPO2 is closely related to the proliferation, migration, and invasion of cancer cells in a variety of tumours." (PMID 37605453, 2023). "Recent studies have reported that the SYNPO2 protein acts as a tumor suppressor and is downregulated in most tumor types to enhance tumor development." (PMID 37544991, 2023). "Our findings help to understand distinct functions of individual SYNPO2 isoforms in different muscle tissues, but also in tumor pathology." (PMID 38201288, 2023). "Mechanically, SYNPO2 regulates tumor growth, metastasis, and invasion via activating the PI3K/AKT/mTOR signal and Hippo signaling pathways." (PMID 37544991, 2023). "In cervical cancer, the inactivation of SYNPO2 expression promotes tumor development by regulating ER, PI3K/AKT, and EMT pathways." (PMID 37544991, 2023). "While the specific role of SYNPO2 in tumor immunity requires further investigation, existing evidence suggests that SYNPO2 indeed plays a significant role in this context." (PMID 37544991, 2023). "This is particularly justified by a number of publications hinting at the reduced expression of SYNPO2 in a variety of tumors, leading to the assumption that it may act as a tumor suppressor." (PMID 38201288, 2023). "The nuclear function of SYNPO2 was suggested to be involved in tumor suppressor activity, whereas cytoplasmic SYNPO2 might have a tumor activator role." (PMID 38201288, 2023). "Thus, exploring the involvement of SYNPO2 in tumor immunity is considered a promising avenue for future research on SYNPO2 molecules." (PMID 37544991, 2023). "Therefore, it is widely thought that nuclear localization of SYNPO2 can inhibit tumor development while high SYNPO2 expression in the cytoplasm accelerates tumor progression." (PMID 37544991, 2023). "For example, the histone deacetylase 9 (HDAC9) gene that displays lower relative expression in infected cells was also expressed at a reduced level in TashAT2 transfected BoMac lines, as was the gene encoding synaptopodin 2 (SYNPO2), which induces focal adhesion and can act as a tumour suppressor." (PMID 37276213, 2023).
tumor (continued). "Finally, among the many other findings providing exciting prospects for future studies, the inter-relationships between tumor microenvironment changes and cytoskeletal events involving, for example, the Flnc and Synpo2 genes raise numerous questions." (PMID 36430209, 2022). "If so, then Synpo2 expression might inhibit tumor cell invasion in 3D environments by repressing bleb formation and amoeboid migration." (PMID 25883213, 2015). "The relationship between Synpo2 expression and tumor development is unclear." (PMID 25883213, 2015). "In addition, gross changes in SYNPO2 isoform expression by different splicing pathways and/or translational control may impact the proposed tumor suppressor activity of SYNPO2 during tumor formation." (PMID 38201288, 2023). "In addition, SYNPO2 was described to play a role in several aspects of tumor development." (PMID 38201288, 2023). "Among them, we selected seven genes associated to cell proliferation and apoptosis that resulted downregulated in tumor samples: BTG1, CCNG1, DMD, EDG1, SEMA3G, SYNPO2, TIMP2." (PMID 39984959, 2025). "The results of rock curve analysis demonstrated that the differential expression of SYNPO2, NR3C2, and CCL28 had a major role in distinguishing tumour tissues from borderline samples." (PMID 38081950, 2023). "A recent publication based on the application of multivariate regression algorithms suitable for higher dimension data identified 3 genes (MAMDC2, SYNPO2 and ARMH4) as biomarkers of gene expression signatures for tumor and marginal tissue zones." (PMID 38188288, 2023). "In particular, GGACT, LXN, THY1, SYNPO2, ACMSD and COLEC11 showed no survival or recurrence associations from the tumor data, suggesting these as unique biomarkers from NAT." (PMID 37575948, 2023). "Using our dataset and another high-quality dataset, we identified proteins that showed clinical prognosis and recurrence associations, of which GGACT, LXN, THY1, SYNPO2, ACMSD and COLEC11 were unique biomarkers identified from NAT that could not be revealed using tumor-based analysis." (PMID 37575948, 2023).
cancer (21 papers, 2009 to 2026). A tumor composed of atypical neoplastic, often pleomorphic cells that invade other tissues. "Mounting studies have indicated that low levels of SYNPO2 may be linked to the development and metastasis of cancer, suggesting that SYNPO2 might be a potential prognostic biomarker and new therapeutic target." (PMID 40853910, 2025). "Moreover, the subcellular localization, promoter methylation and single nucleotide polymorphism (SNP) of SYNPO2 have been associated with cancer progression and clinical outcomes, highlighting its potential as a prognostic or diagnostic target for this patient population." (PMID 37544991, 2023). "Therefore, evaluating SYNPO2 promoter methylation and its expression level could be useful as diagnostic and prognostic cancer predictors." (PMID 37544991, 2023). "SYNPO2 is a structural protein ubiquitously expressed in muscle tissues, where it plays roles in microfilament assembly, cancer progression, and autophagy regulation." (PMID 40000609, 2025). "On the other hand, low SYNPO2 expression and mutation can activate signaling pathways such as the PI3K/AKT/mTOR and the LATS2/YAP/TAZ pathways, promoting cancer development." (PMID 37544991, 2023). "This review focuses on the role of SYNPO2 in cancer, including its generation, epigenetic modification, subcellular localization, and biological function." (PMID 37544991, 2023). "Compared to high SYNPO2 expression in the nucleus, cytoplasmic SYNPO2 expression was significantly upregulated in cancer patients with high recurrence." (PMID 37544991, 2023). "In summary, vitamin C inhibits TNBC metastasis independently of HIF-1α and, likely, by affecting the expression of YAP1 and SYNPO2, two genes in the Hippo pathway which regulate cell mobility and cancer metastasis." (PMID 31817810, 2019). "Our present results provide a second intriguing possibility to explain the effects of Synpo2 on cancer cell invasion." (PMID 25883213, 2015). "Additional studies in both 2D and 3D environments of Synpo2 effects on membrane protrusions should provide further mechanistic insights into the function of this invasive cancer biomarker." (PMID 25883213, 2015). "Notably, nucleosome occupancy-derived scores from RERE and SYNPO2 distinguished recurrent from primary cancer with high accuracy (area under the curve = 0.826)." (PMID 42210783, 2026). "However, emerging evidence suggests that SYNPO2 performs diverse functions in cancers in addition to its role in microfilament assembly." (PMID 37544991, 2023). "Hence, SYNPO2 positively affects cancer, potentially inhibiting apoptosis of cancer cells and maintaining intracellular metabolism." (PMID 37544991, 2023). "Indeed, further research is needed to fully explore the potential of SYNPO2 as a novel target for cancer treatment." (PMID 37544991, 2023). "Previous studies provide some insights into how Synpo2 could affect cancer cell migration responses." (PMID 25883213, 2015). "However, the reasons behind the upregulation of CASA activity and the abnormal down regulation of SYNPO2 protein expression in cancer remain unclear." (PMID 37544991, 2023). "Zheng and Song303 believed that Synaptopodin 2 (SYNPO2) functions as both a structural protein in muscle tissue and an emerging tumor suppressor protein, supported by its positive correlation with favorable cancer prognosis, thereby indicating its crucial role in cancer prevention and treatment." (PMID 39543114, 2024).
Connective Tissue Disease (1 paper, 2024). "We propose that MYH11 and SYNPO2 are novel genes in EMILIN1-related Connective Tissue Disease with both contributing to presentations common to this disorder and Lethal Arteriopathy Syndrome due to Fibulin-4 Deficiency." (PMID 39480826, 2024).
infection (1 paper, 2023). The state of being infected such as from the introduction of a foreign agent such as serum, vaccine, antigenic substance or organism. "Activation of the PI3K/Akt pathway has been described for Theileria infected leukocytes and down-regulation of SYNPO2 (reduced both by TashAT2 and infection) is reported to promote PI3K/Akt signaling and metastasis." (PMID 37276213, 2023).
SYNPO2 also shares sentences with these, for which no sentence is quoted: airway hyperresponsiveness (2 papers); Allgrove syndrome (1); choriocarcinoma (1); congenital myasthenic syndrome (1); developmental delay (1); ependymoma (1); esophageal tumors (1); hydatiform moles (1); lymphoma (1); memory impairment (1); myasthenia gravis (1); myofibrillar myopathy (1); ovarian cancer (1); schistosomiasis (1); stomach cancer (1).